LCT (lactase)
Diseases named in the same sentence as LCT in open-access papers (continued):
Sharing a sentence is not in itself a finding about the gene and the disease.
lactose intolerance (continued). "Overall, lactase supplementation is a valuable strategy in managing lactose intolerance, contributing to improved digestive health and the overall well-being of affected individuals." (PMID 38406012, 2024). "This insight into how simethicone can interact with the efficacy of oral lactase treatment when used to help with infantile gas and bloating possibly represents an unreported drug interaction in the treatment of lactose intolerance in infants." (PMID 39201943, 2024). "Both the age at which lactase activity is reduced and the prevalence of lactose intolerance in adulthood depends on ethnicity." (PMID 39796443, 2024). "Developmental lactose intolerance or neonatal lactose intolerance is observed in premature infants as lactase-expressing enterocytes in the small intestine only start to develop in the third trimester or at a gestational age of at least 34 weeks." (PMID 38337698, 2024). "This excellent lactose-fermenting bacteria breaks down lactose to produce lactic acid, which is particularly beneficial for individuals with lactose intolerance, as they lack the enzyme lactase required to digest lactose." (PMID 38632320, 2024). "The management of neonatal lactose intolerance includes approaches such as low-lactose/lactose-free formula milk and lactase supplementation." (PMID 39201948, 2024). "Symptoms of lactose intolerance occur when the ability to break down lactose to galactose and glucose is reduced, most often due to reduced lactase activity in the small intestine." (PMID 39796443, 2024). "Lactase deficiency, the primary cause of lactose malabsorption, underscores the importance of lactase supplementation in managing lactose intolerance." (PMID 38406012, 2024). "The single nucleotide polymorphism (SNP) C-13910 > T, found 13.9 kb upstream of the LCT gene transcription start site, has been associated with LP in European adults and children based on intestinal biopsy lactase activity and lactose intolerance testing." (PMID 38613035, 2024). "Low levels of the enzyme lactase induce lactose intolerance, which makes it difficult to digest lactose in dairy products." (PMID 38481973, 2024). "Considering the overlap in symptoms of colic and lactose intolerance, further research into the use of lactase for colicky infants is highly likely to be valuable." (PMID 39201943, 2024). "Modifications like chemical conjugation with branched polyethylene glycol (PEG) have shown improved stability in lactase supplementation for lactose intolerance." (PMID 38406012, 2024). "The β-galactosidase, commonly known as lactase, is an important enzyme used in the pharmaceutical and food industries to alleviate symptoms of lactose intolerance and to produce specialised lactose-free foods." (PMID 38373929, 2024). "Whenever newborns exhibited lactose intolerance and significant gastrointestinal symptoms, most respondents preferred exogenous lactase supplementation over switching to lactose-free formula milk as an adjunct to conventional symptomatic medications." (PMID 39201948, 2024). "Primary lactose intolerance (PLI) is the most common form of disaccharide deficiency, characterized by the inability to digest lactose secondary to a low level of the enzyme lactase." (PMID 37371306, 2023). "Although lactose is the main energy source in milk, the production of an enzyme converting it into monosaccharides (lactase) in humans usually falls with age, which often leads to lactose intolerance." (PMID 37958845, 2023). "After weaning, lactase levels decline in 70% of the world’s population, which is the physiological basis of lactose intolerance, a carbohydrate malabsorption, but rarely appears before the age of 5 years." (PMID 36512149, 2023). "Lactose intolerance refers to the clinical picture produced by the insufficient digestion of lactose by intestinal lactase." (PMID 37048365, 2023).
lactose intolerance (continued). "It is reckoned that small amounts of lactase are synthesized by the intestinal flora over a long period of genetic evolution in order to alleviate clinical symptoms of lactose intolerance." (PMID 37444291, 2023). "In recent years, the in-depth study of genetic mechanisms of lactase has provided a new theoretical basis for the epidemiological investigation and prevention of lactose intolerance." (PMID 37444291, 2023). "Small intestinal biopsies in children demonstrated the association of lactase and diamine oxidase (DAO), which are enzymes involved in the mucosa of the small intestine in lactose intolerance (LIT) and histamine intolerance (HIT)." (PMID 37761406, 2023). "In the participants of this study, a possibility of low lactase activity (subclinical lactose intolerance) was suggested because of the H2 in their exhaled breath after consuming milk, although they were not aware of lactose intolerance." (PMID 36568903, 2022). "Rates of hypolactasia or lactose intolerance vary widely by race, but approximately 70% of the world population have hypolactasia, more than 90% of Japanese people have decreased lactase activity, and 20% are lactose intolerant." (PMID 36568903, 2022). "Its activity decreases after weaning as a consequence of the normal maturational down-regulation of lactase activity and leads to lactose intolerance—a syndrome resulting in different symptoms upon the consumption of foods containing lactose." (PMID 35565753, 2022). "The objective evaluation of lactose intolerance is done by measuring enzyme (lactase) activity using biopsy material of the small intestine." (PMID 36568903, 2022). "Bi-07 has high lactase activity, and in 2 clinical trials, it supported lactose digestion in individuals with lactose intolerance." (PMID 36149331, 2022). "There are a few tests available to diagnose lactose intolerance, including hydrogen breath test, quick lactase test, lactose tolerance test, and genetic test." (PMID 35565753, 2022). "The significant lactase activity within the Cytobacillus oceanisediminis NB2 indicated that ingestion/introduction of this microbe can be beneficial for the treatment of lactose intolerance." (PMID 35910631, 2022). "Various treatment modalities were reported for lactose intolerance including lactase supplementation, low‐lactose diet, and potentially, colonic adaptation by probiotics." (PMID 33747481, 2021). "This was a randomized, double‐blind, crossover placebo‐controlled trial to study the effect of lactase tablets on symptoms and hydrogen breath levels in adults with lactose intolerance, confirmed by Lactose HBT." (PMID 33490624, 2021). "The aim was to study the effect of lactase chewable tablets on clinical symptoms and hydrogen breath excretion in patients with lactose intolerance." (PMID 33490624, 2021). "Orally supplemented lactase enzyme significantly reduced the clinical symptoms and hydrogen breath excretion in patients with lactose intolerance." (PMID 33490624, 2021). "Depending on the ethnicity, up to 70% of adults suffer from lactose intolerance as a result of a progressive decrease in intestinal lactase activity." (PMID 33920682, 2021). "Lactose intolerance was investigated in 125 individuals with a SNP analysis with the goal of developing a more reliable genetic test to evaluate lactase persistence." (PMID 34515921, 2021). "It was a randomized, double‐blind, placebo‐controlled trial to observe the effect of marketed lactase supplement on patients with lactose intolerance." (PMID 33490624, 2021). "Data from numerous researchers revealed that some strains of lactic acid bacteria in fermented milk products can relieve lactose intolerance symptoms through secretion of bacterial lactase into the digestive system." (PMID 33747481, 2021).
lactose intolerance (continued). "Probiotic strains with lactase enzyme have been successfully used in combination to improve the lactose intolerance and intolerance symptoms similar to our study using probiotic yoghurt fortified with L. acidophilus and Bifidobacterium sp." (PMID 33747481, 2021). "Investigations of varying results in lactose H2 breath tests led to the suspicion of various LIT phenotypes, for example, relating lactase persistence to lactose intolerance." (PMID 33265924, 2020). "Lactose intolerance (LI) is one of the most common forms of food intolerance and occurs when lactase activity is reduced in the brush border of the small bowel mucosa." (PMID 32443748, 2020). "Symptomatic lactose intolerance is the result of an impaired lactase capacity to properly digest lactose." (PMID 31718111, 2019). "We also investigated the association between SNPs in lactase (LCT), a gene associated with lactose intolerance, with circulating levels of dairy-derived OCSFA." (PMID 29738550, 2018). "Lactose intolerance, characterized by a decrease in host lactase expression, affects approximately 75% of the world population." (PMID 30332787, 2018). "The ability to produce lactase in adulthood or lactose intolerance (hypolactasia) is controlled by the presence of a homozygous G allele in rs4988235 SNV close to LCT." (PMID 29378630, 2018). "This is beneficial to individuals suffering from lactose intolerance because of reduced lactose and lactase produced." (PMID 27207411, 2016). "Lactase persistence is the ability to digest lactose in adulthood and is the inverse of lactose intolerance." (PMID 27042214, 2016). "Lactose intolerance is defined as the clinical syndrome of hypolactasia and lactase maldigestion resulting from the physiologic process of lactose maldigestion." (PMID 27207411, 2016). "For example, regulatory variants located 14 kb upstream and 8 kb downstream from the lactase gene lead to persistence of expression of the lactase gene in adulthood, and lactose intolerance." (PMID 27515598, 2016). "The inability to digest lactose due to insufficient lactase activity results in gastrointestinal symptoms known as lactose intolerance." (PMID 26343715, 2015). "From the point of view of lactose intolerance, these products most likely have advantages similar to yogurt, including reduced lactose content and increased lactase content." (PMID 26404364, 2015). "Because of the presence of lactase-producing cultures, yogurt is often a more easily digestible alternative to milk, and thus more palatable to people who experience symptoms of lactose intolerance." (PMID 26703668, 2015). "Primary lactose intolerance is an inherited trait present in most of the world’s population and is characterized by a gradual decline in lactase level during maturation." (PMID 23326523, 2013). "Current strategies for treatment of lactose intolerance include avoidance of lactose-containing dairy foods (milks, soft cheeses and ice creams) and the use of lactase enzyme supplements with dairy ingestion." (PMID 24330605, 2013). "Notably, no study investigated the effect of estrogens on either lactose digestion and lactase expression or lactase persistence and lactose intolerance." (PMID 41243426, 2025). "Thus, a sex difference in the well‐established lactose intolerance or lactase persistence is yet to be appreciated." (PMID 41243426, 2025). "Primarily, lactose intolerance is related to an impaired release of lactase enzymes because of damaged mucosa, which may further limit dairy intake." (PMID 40238529, 2025). "Lactase supplementation can enhance weight gain in preterm infants without altering the original dietary structure, thus making it an efficacious remedy for neonatal lactose intolerance." (PMID 39201948, 2024). "Primary lactose intolerance is indeed the most common type of LI and is referred to as adult-type hypolactasia, lactase non-persistence (LNP), primary lactase deficiency or hereditary lactase deficiency." (PMID 38337698, 2024).
lactose intolerance (continued). "However, all our study patients had stool reducing-substances test scores ranging from 1+ to 5+, and 86.7% of them benefited from lactase, suggesting that the positivity of the stool reducing-substances test supports the diagnosis of lactose intolerance." (PMID 39201943, 2024). "The primary cause of lactose intolerance is lactase non-persistence, a genetic condition in which the activity of lactase decreases significantly after weaning, a trait that affects the majority of the world’s population." (PMID 39202720, 2024). "Exogenous lactase, sourced from yeast or fungi, provides a reliable therapeutic option for lactase supplementation in formulations like capsules and tablets, effectively alleviating lactose intolerance symptoms." (PMID 38406012, 2024). "Notably, lactase treatment was effective in over 90% of the subjects diagnosed with lactose intolerance." (PMID 39201943, 2024). "However, among patients with primary lactose intolerance, their intestinal lactase expression decreases sharply from its peak at birth to less than 10% of the pre-weaning infantile level during childhood." (PMID 38337698, 2024). "This may indicate the possibility of concurrent lactose intolerance and cow milk protein allergy and the benefit of oral treatment with lactase in these cases." (PMID 39201943, 2024). "Among these, lactose intolerance is a non-immune mediated adverse food reaction caused by a deficiency of the lactase enzyme, causing symptoms like bloating and diarrhea after lactose ingestion." (PMID 38257158, 2024). "However, further research is needed to establish a direct link between the LCT gene, lactose intolerance, and alterations in the gut microbiome." (PMID 37447285, 2023). "For instance, lactase persistent or lactase non-persistent is genetically determined, and primary lactose intolerance is associated with certain genotypes." (PMID 36979637, 2023). "Lack of lactase, a digestive enzyme that prevents the body from hydrolyzing lactose in meals, is the primary cause of lactose intolerance." (PMID 37779717, 2023). "Small intestinal biopsies in children demonstrated the association of lactase and diamine oxidase (DAO), which prompted us to perform hydrogen (H2) breath tests for lactose intolerance (LIT) and determine serum DAO for the evaluation of histamine intolerance (HIT) in pediatric patients with FAPDs." (PMID 37761406, 2023). "Variants in the lactase gene are widely known to cause lactose intolerance, which, per se, has no direct correlation to weight gain." (PMID 38035352, 2023). "Lactose indigestion may lead to lactose intolerance, thus, lactase is necessary to form glucose from lactose for the treatment of lactose intolerance." (PMID 36710963, 2022). "In addition, alcohol interferes with the activity of lactase, which breaks down the milk sugar lactose, resulting in lactose intolerance." (PMID 35493361, 2022). "In the course of celiac disease, secondary lactose intolerance may occur, because of damage to the brush border and transient dysfunction of lactase." (PMID 35565753, 2022). "Similarly as in lactose intolerance, lactase supplementation is used, the exogenous supply of the DAO enzyme has been proposed for HIT." (PMID 34209583, 2021). "In particular, the evolutionary advantage for Northern Europeans was the so-called lactase persistence, a strong positive selection of the lactase allele with no longer occurring lactose intolerance, as a result of the habituation to dairy cattle farming." (PMID 34201342, 2021). "However, there are important differences between our study of low lactase activity and previous studies of lactose intolerance on GI symptoms." (PMID 33036568, 2020). "Symptoms of lactose intolerance may arise from lactose malabsorption, i.e., from the inability to produce lactase at the brush border, but it may also arise from an unfavorable composition of the intestinal microbiome or a history of GI disorders." (PMID 33374779, 2020).
lactose intolerance (continued). "Biological irregularity within the gastric tract results in food intolerances, like that of lactose intolerance, which is caused by the deficiency of the enzyme lactase and not mediated by IgE (a non-IgE immune response)." (PMID 32708567, 2020). "Despite this relative “lactase deficiency” in the preterm infant, clinical symptoms of lactose intolerance are uncommon and the use of lactose is, therefore, not contraindicated." (PMID 31718111, 2019). "Lactase persistence (LP) is a trait in which lactose can be digested throughout adulthood, while lactase non-persistence (LNP) can cause lactose intolerance and influence dairy consumption." (PMID 31405126, 2019). "In addition, the widespread lactose intolerance and lactase insufficiency among Chinese population is another drawback to insufficient consumption of dairy products." (PMID 28872591, 2017). "The CC genotype, which is associated with lactose intolerance/lactase non-persistence was associated with the lowest hip and spine BMD measures and highest fracture rate." (PMID 28684688, 2017). "Lactose intolerance is a genetically programmed decrease of lactase level in adult." (PMID 29201715, 2016). "Even though a previous study showed a higher-than-expected prevalence of lactase down-regulation (14%) among Swedish school children, others have shown that over-reporting of lactose intolerance is frequent even in populations in which lactase down-regulation is common." (PMID 26134827, 2015). "The prevalence of lactose intolerance in Swedish Saami is unknown but among the Nenets, Samoyed people living in north-west Russia, the prevalence of the lactase down-regulating gene is high." (PMID 25905003, 2014). "However, small bowel injury, such as celiac disease, inflammatory bowel disease (IBD) or gastroenteritis can lead to secondary lactose intolerance with reduced lactase activity." (PMID 23326523, 2013). "Unlike the lactose intolerance commonly seen in older children and adults, where there is a deficiency of the enzyme lactase needed to digest lactose, lactose intolerance in breast milk is typically not due to the presence of lactose but rather to other components or conditions." (PMID 40895147, 2025). "Finally, lactase serves as an active ingredient in the treatment of lactose intolerance." (PMID 41471052, 2025). "However, even without genetic loss-of-function (LOF), levels of lactase reduce through life in a majority of individuals, and thus the majority of lactose intolerance actually presents in adulthood." (PMID 41502574, 2025). "Approximately 20% of Hispanic, Asian, and black children younger than 5 years of age have evidence of lactase deficiency and lactose malabsorption, whereas white children typically do not develop symptoms of lactose intolerance until after 4 or 5 years of age.”." (PMID 41008568, 2025). "In addition, 93.88% reported that liquid lactase is suitable for newborns with lactose intolerance." (PMID 39201948, 2024). "Specifically, lactose intolerance is a prevalent condition characterized by the inability to fully digest lactose, a sugar found in milk and dairy products, due to insufficient levels of lactase, the enzyme responsible for breaking down lactose in the small intestine." (PMID 39202720, 2024). "Lactose intolerance, which affects about 65–75% of the world’s population, is caused by a genetic post-weaning deficiency of lactase, the enzyme required to digest the milk sugar lactose, called lactase non-persistence." (PMID 38613035, 2024). "Secondly, the LCT gene and lactose intolerance may have indirect implications for gut inflammation." (PMID 37447285, 2023). "The application of lactase enzyme supplement would improve infant colic due to lactose intolerance, but the supplement will have no impact on infantile colic caused by reasons other than lactose intolerance." (PMID 35922776, 2022). "Thus, the lactase enzyme is required for the treatment of lactose intolerance." (PMID 35910631, 2022).